EGFR (epidermal growth factor receptor)
Diseases named in the same sentence as EGFR in open-access papers (continued):
Sharing a sentence is not in itself a finding about the gene and the disease.
metastatic colorectal cancer (continued). "Anti-EGFR and anti-VEGF antibodies are already used to a large extent to treat metastatic colorectal cancer, therefore overexpression of genes from the EGF and VEGF pathways in sporadic EOCRC could improve the response rates to these targeted therapies." (PMID 25083765, 2014). "With approximately two-thirds of metastatic colorectal cancer patients being wild-type KRAS, this marker could help better use EGFR therapy and spare patients from inappropriate treatment." (PMID 25243170, 2014). "Taken together, the biomarker kinetics suggest that despite minimal anti-tumor activity, vandetanib and cetuximab may adequately suppress target (EGFR and VEGFR2) activity in metastatic colorectal cancer." (PMID 22701615, 2012). "KRAS mutation is a negative predictive factor for treatment with anti-epidermal growth factor receptor (EGFR) antibodies in metastatic colorectal cancer (mCRC)." (PMID 22804917, 2012). "Activating somatic mutations in the KRAS oncogene is an example of a biomarker, which predicts non-response to therapies targeting the epidermal growth factor receptor (EGFR) in metastatic Colorectal Cancer (mCRC)." (PMID 23173730, 2012). "In addition, panitumumab (Vectibix®) is developed as a fully human IgG2-isotype mAb against ErbB1 and is approved for the treatment of patients with EGFR-expressing metastatic colorectal cancers." (PMID 23202898, 2012). "KRAS mutation is a negative predictive factor for treatment with anti-epidermal growth factor receptor antibody in metastatic colorectal cancer (CRC)." (PMID 21364579, 2011). "Clinical trial data indicate that the presence of mutated BRAF V600E serves as a negative prognostic indicator for patients diagnosed with metastatic colorectal cancer (mCRC), potentially indicating resistance to EGFR-antibody therapy, particularly in heavily treated individuals." (PMID 39682117, 2024). "Furthermore, HER2 overexpression is recognized as a negative prognostic factor and a negative predictive biomarker for anti-EGFR treatment in metastatic colorectal cancer, reinforcing its role in poor outcomes across different histologic types." (PMID 39123483, 2024). "Furthermore, along with chemotherapy, targeted therapies such as monoclonal antibodies targeting epidermal growth factor receptor (EGFR) (e.g., cetuximab) and vascular endothelial growth factor (VEGF) (e.g., bevacizumab) are the gold standard treatments for advanced or metastatic colorectal cancer." (PMID 36793708, 2023). "When AREG was analyzed separately as a dichotomous variable, the CALGB 80203 and PICCOLO trials showed that AREG mRNA expression and AREG IHC were neither prognostic markers nor predictive markers of benefit from EGFR-targeted therapy in RAS wt metastatic colorectal cancer." (PMID 37974093, 2023). "The results suggest that patients with metastatic colorectal cancer resistant to cetuximab and those with concomitant HER-2 amplification and ineffective clinical treatment may benefit from the combination of HER-2 inhibitors and EGFR inhibitors." (PMID 37344821, 2023). "Regorafenib is used to treat metastatic colorectal cancer patients who have previously received fluoropyrimidine-, oxaliplatin-, and irinotecan-based chemotherapy, anti-vascular endothelial growth factor (VEGF) therapy, and (if wild-type RAS) anti-epidermal growth factor receptor (EGFR) treatment." (PMID 35449153, 2022). "However, clinical studies have shown that metastatic colorectal cancer (mCRC) patients respond to anti-EGFR mAbs regardless of EGFR status." (PMID 35740594, 2022). "Similarly, among patients with metastatic colorectal cancer (mCRC), a RAS mutation is used as a predictive biomarker to select patients who will not benefit from epidermal growth factor receptor (EGFR) antibody therapy." (PMID 36547194, 2022).
metastatic colorectal cancer (continued). "Currently, anti-epidermal growth factor receptor (EGFR) monoclonal antibodies (mAbs) cetuximab and panitumumab, anti-vascular endothelial growth factor (VEGF) mAb bevacizumab, and anti-VEGFR2 mAb ramucirumab are approved for the treatment of patients with metastatic colorectal cancer." (PMID 33562755, 2021). "Interestingly, duligotuzumab (MEHD7945A), a BsAb targeting EGFR and HER3, showed no clinical benefit in comparison to cetuximab (anti-EGFR mAb) in phase 2 trials in patients with metastatic colorectal cancer or head and neck squamous cell carcinoma." (PMID 32989604, 2020). "Previous studies have demonstrated that left-sided tumors have better prognoses than right-sided tumors in RAS wild-type mCRC (metastatic colorectal cancer) patients, while anti-EGFR mAbs appear to have no advantage compared with bevacizumab for right-sided tumors in these patients." (PMID 30296945, 2018). "Treatment of metastatic colorectal cancer (CRC) patients may include EGFR-targeted therapy if the tumor does not harbor an activating downstream RAS mutation." (PMID 28199979, 2017). "Patients with metastatic colorectal cancer whose disease has progressed on oxaliplatin- and irinotecan-containing regimens may benefit from EGFR-inhibiting monoclonal antibodies if they do not contain mutations in the KRAS gene (are “wild type”)." (PMID 27246726, 2016). "Treatment of metastatic colorectal cancer (CRC) with traditional 5-fluorouracil (5FU)-based chemotherapy has been modified, with addition of oxaliplatin, irinotecan and monoclonal antibodies targeting vascular endothelial growth factor (VEGF) and the epidermal growth factor receptor (EGFR)." (PMID 27340376, 2016). "Presence of K-ras wild type gene predicts response to epidermal growth factor receptor (EGFR) monoclonal antibodies such as cetuximab or panitumumab, and they are usually combined with FOLFIRI (or FOLFOX in the case of panitumumab) in the treatment of metastatic colorectal cancer." (PMID 25866690, 2015). "However, recent studies showed that KRAS G13D mutation and codon 12 mutations are actually not created equal in predicting clinical outcomes of anti-EGFR therapy in metastatic colorectal cancer (mCRC) patients." (PMID 23874486, 2013). "Two monoclonal antibodies (MoAb) targeted at epidermal growth factor receptor (EGFR), the chimeric IgG1 MoAb cetuximab and the fully humanized IgG2 panitumumab, have proven to be effective in combination with chemotherapy or as single agent for treatment of metastatic colorectal cancer (mCRC)." (PMID 22586484, 2012). "Furthermore, low- but not high-level EGFR protein expression on KRAS wild-type metastatic colorectal cancer cells may be a prerequisite for successful anti-EGFR antibody therapy." (PMID 32155907, 2020). "Combination therapy comprising anti-epidermal growth factor receptor (EGFR) antibody and anti-cytotoxic drugs has shown a survival benefit as a first-line, as well as a second-, third-, and salvage-line chemotherapy for patients with metastatic colorectal cancer (mCRC) without RAS mutations." (PMID 31637554, 2019). "Duligotuzumab (MEHD7945A), a BsAb targeting EGFR and HER3, showed no clinical benefit in comparison to cetuximab (anti-EGFR mAb) in phase 2 trials in patients with metastatic colorectal cancer or head and neck squamous cell carcinoma." (PMID 40057807, 2025). "Currently, anti-EGFR therapy is mainly used for treating metastatic colorectal cancer patients with wild-type RAS/BRAF, since RAS/BRAF mutant patients do not respond well to anti-EGFR therapy." (PMID 36339570, 2022). "Therefore, anti-EGFR antibody treatment was only indicated when patients had no mutations in KRAS or BRAF until recently, combination treatment of cetuximab with encorafenib and binimetinib was approved for the treatment of patients with metastatic colorectal cancer harboring a BRAF V600 E mutation." (PMID 35035479, 2022).
metastatic colorectal cancer (continued). "Treatment of non-resectable metastatic colorectal cancer (mCRC) involves chemotherapy based on 5-fluorouracil, oxaliplatin and irinotecan and monoclonal antibodies targeting VEGF or EGFR." (PMID 34771635, 2021). "In conclusion, high baseline plasma AREG levels predicted worse PFS in patients with RAS/BRAF wild-type metastatic colorectal cancer treated with palliative first-line cetuximab plus FOLFIRI chemotherapy, but not with non-EGFR-directed second-line treatment." (PMID 34893673, 2021). "The anti-epithelial growth factor receptor (EGFR) monoclonal antibodies (mAbs) cetuximab and panitumumab improve survival in patients with RAS wild-type (WT) metastatic colorectal cancer (mCRC), but do not yield a significant survival benefit in patients with right-sided or RAS mutant (MT) mCRC." (PMID 39066951, 2024). "Another study demonstrated that the coexpression of EGFR protein and their ligands, TGFα, EGF, amphiregulin and betacellulin, could be a negative predictor of cetuximab effectiveness in metastatic colorectal cancer." (PMID 32155907, 2020).
head and neck cancer (624 papers, 1990 to 2026). A primary or metastatic malignant neoplasm affecting the head and neck. "Our search included major databases such as PubMed, Embase, and Web of Science with keywords such as EGFRvIII, EGFR variants, and head and neck cancer, and stratified the results using Boolean logic to enhance relevance and specificity." (PMID 41821890, 2026). "Significant overexpression of WBP5 was observed in HNSCC, and it showed a positive association with EGFR, which serves as the target of Cetuximab, a key therapeutic agent for head and neck cancer treatment." (PMID 40002180, 2025). "The EGFR pathway is activated by ligand binding, and EGFR overexpression is linked to malignancies like colorectal and head and neck cancer." (PMID 40332084, 2025). "EGFR was previously associated with radioresistance in various cancers, including oropharyngeal carcinoma, head and neck cancer, and GBM." (PMID 40015963, 2025). "EGFR mutations are rare in head and neck cancer, although they have been described in small cohorts as a potential therapeutic target." (PMID 39590164, 2024). "In head and neck cancers, EGFR is overexpressed in 80–90% of cases and is linked to poor prognosis and less favorable treatment outcomes." (PMID 39339232, 2024). "On the other hand, EGFR, a receptor tyrosine kinase, is overexpressed in a significant majority of head and neck cancers and is associated with aggressive tumor behavior and resistance to conventional therapies." (PMID 39339232, 2024). "AuNPs that were EGFR-targeted allowed for efficient CT visualization of the tumor-associated vasculature in mouse head and neck carcinomas." (PMID 38500178, 2024). "Recurrent epidermal growth factor receptor (EGFR)-activating mutations have been identified in a rare form of head and neck cancer known as sinonasal squamous cell carcinoma (SNSCC), a malignant disease with a 5-year mortality rate of ~40%." (PMID 35053553, 2022). "In head and neck cancer, nicotine causes the phosphorylation of EGFR by regulating α7 nAChR, leading to lymph node metastasis and cetuximab resistance in HNSCC cells." (PMID 36284268, 2022). "Increased IGF‐1R signalling is associated with a poor response to anti‐EGFR treatment in head and neck cancer cells." (PMID 34528373, 2021). "For instance, trough levels or clearance values were repeatedly associated with the efficacy of anti-EGFR cetuximab either in colorectal or head and neck cancers." (PMID 34451893, 2021). "EGFR overexpression can be observed in 80–90% of patients with head and neck cancer (HNC) and associated with poor overall survival in clinical practice." (PMID 33668218, 2021). "Increased EGFR expression has been associated with poorer clinical outcome in a number of malignancies, including bladder, breast, lung, and head and neck cancers." (PMID 32012988, 2020). "Logistic regression analysis was then used to determine the clinicopathologic characteristics associated with high EGFR expression in head and neck malignant tumors." (PMID 33273921, 2020). "Epidermal growth factor receptor (EGFR) overexpression is associated with the development of head and neck cancer (HNC) and represents one of the main therapeutic targets for this disease." (PMID 30765872, 2019). "The importance of EGFR as a high-risk indicator for progressive disease or poor prognosis has been demonstrated in head and neck cancers." (PMID 30138436, 2018). "There is evidence that in head and neck cancer, the NF‐κB transcriptional factor is constitutively activated and linked to activation of known oncogenic pathways, such EGFR/Ras/RAF/MAPK, Akt/PI3K/mTOR, ΙΚΚ/NF‐κB, STAT3 and wnt/β‐catenin." (PMID 29911313, 2018). "In head and neck cancer cells, high levels of EGFR are associated with radiation resistance, whereas the anti-EGFR monoclonal antibody can improve the radiosensitivity of cells." (PMID 28968954, 2017).
head and neck cancer (continued). "GRP78 overexpression was also associated with a poor prognosis in head and neck carcinoma, but the correlation of EGFR and ERS signalling pathways in head and neck squamous cell carcinoma has not been reported in histological studies." (PMID 29232380, 2017). "EGFR overexpression is associated with tumor progression and poor prognosis in many types of cancers including head and neck cancers." (PMID 25918252, 2015). "EGFR overexpression has been closely associated with tumor progression, therapeutic resistance and poor clinical outcome in head and neck cancer and other cancer types." (PMID 24586249, 2014). "Mutational activation of EGFR is implicated in many cancers including lung, head and neck cancer, and clinical and cancer genome sequencing studies have identified hundreds of mutations in the protein kinase domain." (PMID 24743239, 2014). "Around 80% of head and neck cancer patients overexpress the epidermal growth factor receptor (EGFR) which is linked to poor prognosis." (PMID 23862155, 2013). "The EGFR pathway is abnormally activated in HNSCC and overexpression of EGFR has been associated with poor response to chemotherapy and poor survival in head and neck cancer patients." (PMID 22629428, 2012). "The overexpression of EGFR in head and neck cancer is associated with an advanced stage, lymph node metastasis, low survival rate, and poor response to radiation therapy." (PMID 23231994, 2012). "Overexpression of the epidermal growth factor receptor (EGFR) is a hallmark of head and neck cancers and confers increased resistance and inferior survival rates." (PMID 21912620, 2011). "In the present study, we examined 20 head and neck cancer specimens and 4 cell lines for mutations in either exon and report here the high conservation of these sequences of the EGFR gene." (PMID 20130810, 2009). "The association between anti-EGFR therapy and radiation is based on consistent preclinical data confirmed at the clinical level, particularly in head and neck cancer." (PMID 18577994, 2008). "This background led us to undertake the present experimental study on head and neck cancer xenograft considering the triple association of EGFR targeting by erlotinib combined with the anti-angiogenic agent bevacizumab and associated with irradiation." (PMID 18577994, 2008). "Overexpression of EGFR and Her-2 have been reported to be associated with higher grades or reduced survival in a variety of cancers, including breast, colorectal, and head and neck cancers." (PMID 12915878, 2003). "Epidermal growth factor receptor (EGFR) has been particularly well studied in head and neck cancer (HNC) because of its association with the cellular mechanisms involved in tumour progression." (PMID 11875748, 2002). "On the other hand, cyclin D1 (encoded by CCND1, which frequently shows gene amplification in head and neck cancers) is a key downstream effector of EGFR signaling and associated pathways, promoting cell cycle progression and contributing to the hyperproliferative phenotype of OL." (PMID 40805130, 2025). "For head and neck cancer, only <5% of tumors contain EGFR mutations." (PMID 40940319, 2025). "Importantly, this was the first ever study that specifically evaluated EGFR mutations—which are rare in head and neck cancer overall—in SNSCC and ISP." (PMID 35053553, 2022). "Furthermore, the G33K and N56K mutations, which are also located in domain I, cause ligand-independent EGFR phosphorylation in head and neck cancer." (PMID 33705793, 2021). "For example, head and neck cancer patients carrying the A allele at rs2227983 in their epidermal growth factor receptor (EGFR) gene have greatly increased treatment response and survival after cetuximab (an EGFR antagonist) treatment." (PMID 34437536, 2021).